MYF5 (myogenic factor 5)
Description:
Transcriptional activator that promotes transcription of muscle-specific target genes and plays a role in muscle differentiation. Together with MYOG and MYOD1, co-occupies muscle-specific gene promoter core region during myogenesis. Induces fibroblasts to differentiate into myoblasts. Probable sequence specific DNA-binding protein.
Synonyms: bHLHc2; EORVA
Tractability: No criterion of Open Targets' tractability assessment is met for any kind of drug.
Gene: Protein-coding gene on chromosome 12 (80,716,912 to 80,719,671, forward strand). Ensembl gene ENSG00000111049.
Subcellular location: Nucleus
Subcellular location (Human Protein Atlas): Nucleoplasm
Pathways (Reactome):
Developmental Biology: Myogenesis
Signal Transduction: TGFBR3 expression
Gene Ontology:
Molecular function: protein binding; DNA-binding transcription factor activity, RNA polymerase II-specific; E-box binding; RNA polymerase II cis-regulatory region sequence-specific DNA binding; DNA-binding transcription activator activity, RNA polymerase II-specific; protein dimerization activity; sequence-specific DNA binding
Biological process: muscle cell fate commitment; muscle organ development; positive regulation of myoblast differentiation; positive regulation of skeletal muscle fiber development; regulation of transcription by RNA polymerase II; skeletal muscle cell differentiation; skeletal muscle tissue development; animal organ development; positive regulation of transcription by RNA polymerase II; regulation of DNA-templated transcription; tissue development
Cellular component: nucleoplasm; nucleus; chromatin; RNA polymerase II transcription regulator complex
Genetic constraint (gnomAD): Loss-of-function variants: 19 observed, 21.97 expected, observed/expected ratio (o/e) 0.86, 90% interval 0.6 to 1.27. The upper end of that interval is the gene's LOEUF score, 1.27, which puts it in group 5 of 6, group 1 being the genes least tolerant of losing a copy. Missense variants: 348 observed, 343.87 expected, observed/expected ratio (o/e) 1.01, 90% interval 0.93 to 1.11. Synonymous variants: 141 observed, 134.47 expected, observed/expected ratio (o/e) 1.05, 90% interval 0.91 to 1.21.
Homologues: Orthologues: chimpanzee MYF5 (100% identical), macaque MYF5 (99% identical), rabbit MYF5 (96% identical), guinea pig MYF5 (94% identical), pig MYF5 (94% identical), rat Myf5 (90% identical), mouse Myf5 (89% identical), dog MYF5 (88% identical), tropical clawed frog myf5 (71% identical), zebrafish myf5 (57% identical), Drosophila melanogaster nau (41% identical), Caenorhabditis elegans hlh-1 (31% identical). Paralogues in human: MYOD1 (49% identical), MYF6 (39% identical), MYOG (34% identical).
Diseases named in the same sentence as MYF5 in open-access papers:
MYF5 is named in the same sentence as 54 diseases in open-access papers, as found by Europe PMC text mining. Sharing a sentence is not in itself a finding about the gene and the disease. The quoted sentences say what the papers report.
rhabdomyosarcoma (9 papers, 1991 to 2025). A rare aggressive malignant mesenchymal neoplasm arising from skeletal muscle. "Exogenous Wnt1 activates Myf5 expression, resulting in MuSC activation and/or proliferation, as shown in rhabdomyosarcomas." (PMID 34087215, 2021). "The binding of SNAIL to E-box sequences in the myogenic factor 5 (MYF5) promoter and recruiting histone deacetylases (HDACs) was described in the regulation of rhabdomyosarcoma development." (PMID 31947678, 2020). "Further transcriptomics and mechanistic studies in zebrafish and human rhabdomyosarcomas have demonstrated the potent role of the transcription factors MYF5 and MYOD in the development and growth of muscle tumors." (PMID 30775367, 2019). "Rhabdomyosarcomas express b-Helix-loop-Helix (bHLH) myogenic regulatory transcription factors (MRFs), including MYF5 and MYOD but fail to activate terminal muscle differentiation programs." (PMID 28080960, 2017). "Northern analysis of tumour RNA has been used to examine the expression of members of the myf family of muscle determining genes (myf3, myf4, myf5 and myf6) in a series of 20 rhabdomyosarcomas." (PMID 1764365, 1991). "Rhabdomyosarcomas (RMS) are high-grade malignant tumors exhibiting partial myogenic differentiation due to aberrant expression of muscle regulatory factors (MRFs) such as myogenic factor 5 (MYF5), myoblast determination protein 1 (MYOD), and myogenin (MYOG)." (PMID 41425252, 2025). "Previous research has suggested that MYF5+ MSCs may contribute to the development of rhabdomyosarcoma." (PMID 40107247, 2025). "Similarly, a study performed with an inducible zebrafish embryonal rhabdomyosarcoma model has identified the shared upregulation of MYF5 mRNA in zebrafish and human expression datasets based on GSEA comparisons." (PMID 30775367, 2019). "The upregulation and oncogenic role of myogenic transcription factors (MYF5, MYOD) has been described for rhabdomyosarcoma, a pediatric malignancy of muscle." (PMID 37906280, 2023). "Our data supports a previously unappreciated role for MYF5 and MYOD in regulating growth, proliferation, and TPC activity in rhabdomyosarcoma." (PMID 28080960, 2017). "Rhabdomyosarcoma (RMS) is a pediatric malignacy of muscle with myogenic regulatory transcription factors MYOD and MYF5 being expressed in this disease." (PMID 28080960, 2017). "Notably, the epithelial-to-mesenchymal transition (EMT) transcription factor Snail has been reported to regulate MYF5 expression, thereby promoting rhabdomyosarcoma progression, indicating a potential link between tumor EMT processes and MYF5 expression." (PMID 40107247, 2025).
Obesity (6 papers, 2016 to 2023). Accumulation of substantial excess body fat. "Our data show that Dnmt3b deficiency in Myf5+-brown fat precursor cells inhibits thermogenic program in brown fat, decreases energy expenditure, and promotes diet-induced obesity and insulin resistance in female mice." (PMID 34439754, 2021). "In consistence with our prior findings on Dnmt1 or 3a, deletion of Dnmt3b at early stage of brown fat development using Myf5-Cre also promoted diet-induced obesity and insulin resistance, which was associated with the induction of myogenic program in brown fat." (PMID 34439754, 2021). "Hung and colleagues showed that Rictor loss in the Myf5+ precursor lineage (Myf5-Cre) shifts BAT metabolism to a more oxidative and less lipogenic state and protects mice against obesity and metabolic disease." (PMID 37511253, 2023). "Obesity in the aged mice seemed to alter this pattern, with a decreased mRNA expression of Myf5 and Myog, and increased Myod expression compared with the aged lean mice." (PMID 36296923, 2022). "To determine the role of brown fat Dnmt3b in the regulation of diet-induced obesity, we generated a genetic model with deletion of Dnmt3b in brown fat-skeletal muscle lineage precursor cells (3bKO) by crossing Dnmt3b-floxed (fl/fl) mice with Myf5-cre mice." (PMID 34439754, 2021). "It is not clear, however, whether Dnmt3b deletion in Myf5 lineage adipocytes would affect the formation of glycolytic beige adipocytes, contributing to the decreased energy expenditure and increased obesity observed in 3bKO mice." (PMID 34439754, 2021).
synovial sarcoma (6 papers, 2013 to 2024). "Cre/LoxP-driven mouse synovial sarcoma (SS) most readily forms in a Myf5-expressing skeletal muscle-specific lineage, whereas fusion oncogene expression in early myogenic precursors (Pax3/Pax7) was fatal and myofiber expression (Myf6) caused myopathy." (PMID 38916046, 2024). "In synovial sarcoma, exogenous expression of SYT-SSX2 fusion gene in the skeletal-muscle-specific Myf5 expressing lineage induced the formation of synovial sarcomas in vivo." (PMID 23880362, 2013). "In the Myf5-Cre linage, tumors formed with 100% penetrance, presented both biphasic and monophasic histology and expressed a gene signature that partially overlapped with that of human synovial sarcoma." (PMID 33918045, 2021). "Moreover, the expression of the EWS-ATF1 chromosomal translocation product in neural crest-derived cells resulted in clear cell sarcomas, and when SYT-SSX expression was induced in Myf5-expressing myoblasts, 100% of mice developed synovial sarcoma-like tumors." (PMID 27191748, 2017). "Interestingly, primary synovial sarcomas, which can be induced experimentally in mice under a Myf5 promoter, have been reported in the human pancreas – another exocrine gland." (PMID 25883905, 2015). "SyS distribution, although always near to skeletal structures, was slightly different from that observed in hSS2/Myf5–Cre mice, intriguingly suggesting a non-myogenic origin for synovial sarcomas." (PMID 36765545, 2023). "When the conditional SS18-SSX2 mice were bred with Myf5–Cre mice, about 8% of the progeny died within 2 months with smaller body dimensions but no tumors, and the rest developed multiple synovial sarcomas by the age of 3–5 months with complete penetrance (100%)." (PMID 36765545, 2023).
External ophthalmoplegia (4 papers, 2019 to 2024). Paralysis of the external ocular muscles. "Variants in MYF5 were found to cause external ophthalmoplegia with rib and vertebral anomalies (EORVA), a rare recessive condition." (PMID 38927634, 2024). "Patient I35 had two pathogenic nonsense variants on MYLK (OMIM: *600922) and MYF5 (OMIM: *159990), associated with aortic aneurysm and familial thoracic (OMIM: 613780), and external ophthalmoplegia with rib and vertebral anomalies (OMIM: 618155), respectively." (PMID 36361644, 2022). "The mutation (p.Arg95Cys) located at the bHLH domain of Myf5 can impair Myf5 nuclear localization and transcriptional activity, which leads to external ophthalmoplegia, rib, and vertebral anomalies in humans." (PMID 31477002, 2019). "External ophthalmoplegia with rib and vertebral anomalies (EORVA) is characterized by congenital nonprogressive external ophthalmoplegia, ptosis, scoliosis, torticollis, vertebral, and rib anomalies, caused by homozygous mutations in the myogenic factor 5 gene (MYF5) located on chromosome 12q21.31." (PMID 35186005, 2022).
muscular dystrophy (4 papers, 2016 to 2022). Muscular dystrophy (MD) refers to a group of more than 30 genetic diseases characterized by progressive weakness and degeneration of the skeletal muscles that control movement. "Therefore, increasing the Myf5 positive satellite cell pool is a plausible strategy to enhance muscle regenerative capacity and combat some degenerative diseases caused by physiological aging or muscular dystrophies." (PMID 29593538, 2018). "In this study, we generated skeletal muscle-selective Myf5-Ispd-cKO mice and confirmed that ISPD is responsible for CDP-Rbo production in vivo and that the loss of CDP-Rbo production leads to muscular dystrophy." (PMID 35422047, 2022). "The considerable variability in expression of Akt and S6 proteins in Myf5/Fktn KO mice may reflect differences in the severity of muscular dystrophy within the aged knockout cohort." (PMID 27257474, 2016).
scoliosis (3 papers, 2022 to 2025). A congenital or acquired spinal deformity characterized by lateral curvature of the spine. "For example, the human MYF5 variant R95C, which affects the dMeR modeled here, diminishes MYF5 binding and nuclear localization and produces a clinical disorder characterized by congenital ophthalmoplegia, scoliosis, and vertebral and rib anomalies." (PMID 41516148, 2025).
dystroglycanopathy (2 papers, 2016 to 2022). "A small number of Myf5-Ispd-cKO mice showed incomplete loss of α-DG glycosylation and a much milder muscle phenotype, consistent with previously reported variation in the individual phenotypes of other models of dystroglycanopathy generated using Myf5-Cre KI mice." (PMID 35422047, 2022). "To determine whether Akt/mTOR signaling is altered in dystroglycanopathy mice, we examined the activation status of pathway proteins in fasted Myf5/Fktn KO muscle from mice aged 17–25 weeks, an age range with substantive remodeling of the muscle compartment." (PMID 27257474, 2016).
muscle atrophy (2 papers, 2023 to 2025). The loss of muscle tissue due to inactivity or disease. "Muscle atrophy was triggered by the PBM-based diet, but this effect was improved with FPHs supplementation, as demonstrated by a significant increase in muscle fiber quantification (fiber density, hyperplasia, and hypertrophy) and muscle health relevant gene expression (IGF-1, myf5, and MyoG)." (PMID 37057066, 2023).
atherosclerosis (1 paper, 2022). A disease characterized by the build-up of fatty material and calcium deposition in the arterial wall resulting in partial or complete occlusion of the arterial lumen. "Similarly, Myf5 (identified to be the marker for adipocyte progenitor/precursor cells) expression has been associated with atherosclerosis in SMC proliferation to initiate neointimal hyperplasia (NIH)." (PMID 35531433, 2022). "The eight major genes upregulated in the carotid vessels (IL18, PDGFRA, IL17, LOX1, TLR4, MYF5, IL1B, and PDPN) were intimately involved in the pathologic progression of atherosclerosis and NIH." (PMID 35531433, 2022).
Atrophy (1 paper, 2023). Any weakening or degeneration, especially through lack of use. "Previously, NPN_1 was shown to induce expression of genes involved in myogenesis (mTOR and MYF5) in a murine model of atrophy as well as p-S6 expression in vitro." (PMID 36839344, 2023).
Cerebro-costo-mandibular syndrome (1 paper, 2013). Cerebro-costo-mandibular syndrome (CCMS) is characterized at birth by posterior rib gaps and orofacial anomalies reminiscent of Pierre Robin syndrome (see this term) that include palatal defects (short hard palate, absent soft palate, absent uvula), micrognathia and glossoptosis. "Intriguingly, Myf5 is one of the genes hypothesized to have a causal role in cerebro-costo-mandibular syndrome, a rare multiple congenital anomaly syndrome characterized by absent ossification of the posterior rib-cage and micrognathia." (PMID 23408915, 2013).
congenital muscular dystrophy (1 paper, 2022). A muscular dystrophy that is characterized by diminished muscle tone (hypotonia), progressive muscle weakness and degeneration (atrophy), abnormally fixed joints, spinal rigidity, and delays in reaching motor milestones such as sitting or standing unassisted. "The Myf5-Ispd-cKO mice exhibited severe pathological hallmarks including fiber size variation and fibrotic tissue infiltration, which are often observed during the clinical course of congenital muscular dystrophy caused by ISPD mutations." (PMID 35422047, 2022).
congenital ophthalmoplegia (1 paper, 2024). "With four MYF5 variants now discovered, genetic testing and paediatric assessment for extra-ocular features should be considered in all cases of congenital ophthalmoplegia." (PMID 38927634, 2024).
gastric cancer (1 paper, 2016). A primary or metastatic malignant neoplasm involving the stomach. "A study on the expression of genes involved in muscle regeneration (Pax7, MyoD, Myf5, nMyHC, necdin) in gastric cancer patients found that Pax7 was significantly increased in all disease stages compared to controls, whereas MyoD and necdin were only upregulated in early disease stages." (PMID 26856534, 2016).
glioblastoma (1 paper, 2017). The most malignant astrocytic tumor (WHO grade IV). "Our data also suggests, that like T-ALL and glioblastoma, the MYF5 and MYOD bHLH proteins regulate common molecular pathways in self-renewal and growth of both normal and malignant muscle." (PMID 28080960, 2017).
hyperglycaemia (1 paper, 2024). "RT-qPCR revealed that the expression of Myf5 and Pax3, which are markers of myoblasts, were upregulated by intrauterine hyperglycaemia." (PMID 39043630, 2024).
hyperlipidemia (1 paper, 2022). "Interestingly, the TLR4 signaling has been reported to be associated with Myf5 expression suggesting the association between pro-inflammatory milieu following the hyperlipidemia and/or intimal lipid burden with subsequent mobilization/activation of SMCs via Myf5." (PMID 35531433, 2022).
intrauterine growth retardation (1 paper, 2021). "A recent study reported that PAX7, MYOD, MYF5 and MYOG within M. semitendinosus were downregulated in female piglets suffering from intrauterine growth retardation (IUGR) compared with normal pigs from birth to 100 dpn47." (PMID 34183762, 2021).
ischemia (1 paper, 2025). A hypoperfusion of the BLOOD through an organ or tissue caused by a PATHOLOGIC CONSTRICTION or obstruction of its BLOOD VESSELS, or an absence of BLOOD CIRCULATION. "AT-derived EVs benefit skeletal muscletrophism, protecting against ischemic degeneration and enhancing regeneration ina hindlimb ischemia model via increased MyoD, Myf5, and Pax7 expression." (PMID 39916853, 2025).
lipoma (1 paper, 2015). A benign, usually painless, well-circumscribed lipomatous tumor composed of adipose tissue. "Deletion of Pten in adipocytes leads to striking lipoma formation when targeting MYF5 expressing cells, but surprisingly did not affect lipid mass when deleted from mature aP2-cre targeted fat cells." (PMID 26317218, 2015).
lipomatosis (1 paper, 2020). A neoplastic process characterized by diffuse overgrowth of mature adipose tissue. "Specifically, activation of PI3K-AKT signalling selectively in Myf5+ mouse mesenchymal precursors was shown to lead to an increase in AP numbers and profound lipomatosis." (PMID 32493999, 2020).
malnutrition (1 paper, 2018). Inadequate nutrition resulting from poor diet, malabsorption, or abnormal nutrient distribution. "Compared with AFG, the decreased transcription levels of Myf-5, MRF4 as well as IGF-2 in most of tested positional muscle tissues of GFG, could be induced by malnutrition." (PMID 29632496, 2018).
ovarian carcinoma (1 paper, 2020). A malignant neoplasm originating from the surface ovarian epithelium. "For instance, MYF5 and MYOD as transcription factors are mutually-exclusively expressed, and each is required for sustained tumor growth; TCF12 is a poor prognostic factor of ovarian cancer and prostate cancer." (PMID 33178820, 2020).
Sepsis (1 paper, 2025). Sepsis is defined as life-threatening organ dysfunction caused by a dysregulated host response to infection. "In TA, sepsis increased expression of markers of muscle regeneration Myf5 and Myog, but not Pax7 and Myod1." (PMID 41385533, 2025).
spindle-cell tumors (1 paper, 2011). "Histopathology of RMS mainly presented as embryonic (ERMS) or spindle-cell tumors, which expressed myogenic factors to various degrees, such as myogenin, Myf5, or desmin (not shown)." (PMID 21533183, 2011).
teratoma (1 paper, 2020). A non-seminomatous germ cell tumor characterized by the presence of various tissues which correspond to the different germinal layers (endoderm, mesoderm, and ectoderm). "Western blot analysis revealed that Myf5 and M-cadherin protein levels were also significantly reduced in Pax7−/− teratomas." (PMID 32552916, 2020). "The levels of Myf5 and Cdh15 mRNA and proteins were lower in Pax7−/− teratomas, what indicates abnormal formation or maintenance of satellite cell population." (PMID 32552916, 2020). "Next, the proportion of Myf5+ cells localized within the satellite cell niche, calculated as a the percentage of all nuclei in the muscle tissue area, was significantly lower in Pax7−/− teratomas in comparison to Pax7+/+ teratomas." (PMID 32552916, 2020).
ZIKV infection (1 paper, 2021). "However, ZIKV infection did not interfere with Myf5 mRNA levels and reduced the expression of MyoD, two early myogenic commitment factors." (PMID 34468171, 2021).